PKN2 (protein kinase N2)
Diseases named in the same sentence as PKN2 in open-access papers (continued):
Sharing a sentence is not in itself a finding about the gene and the disease.
cardiac hypertrophy (2 papers, 2022 to 2026). "This study addresses the role of PKN2 throughout development, from its importance in cardiomyocytes in the embryo, through influence on cardiac remodelling in pathological cardiac hypertrophy in the adult heart and to a potential role in aging." (PMID 35730579, 2022). "It is concluded that cardiomyocyte PKN2 is essential for heart development and the formation of compact myocardium and is also required for cardiac hypertrophy in hypertension." (PMID 35730579, 2022). "Cardiac hypertrophy resulting from hypertension induced by angiotensin II was reduced in these haploinsufficient PKN2 mice relative to wild-type littermates, with suppression of cardiomyocyte hypertrophy and cardiac fibrosis." (PMID 35730579, 2022). "In vivo studies suggest there may be redundancy between PKN1 and PKN2 in cardiomyocytes, and double knockout of both kinases simultaneously in cardiomyocytes inhibits cardiac hypertrophy in pressure-overload conditions induced by transverse aortic constriction (TAC) or angiotensin II (AngII)." (PMID 35730579, 2022). "This contrasts with a recent study reporting that tamoxifen-inducible, cardiomyocyte-specific knockout of both PKN1 or PKN2 (not either gene alone) in adult mice, reduced cardiac hypertrophy in models of pressure-overload, namely thoracic aortic constriction (TAC) or AngII." (PMID 35730579, 2022).
melanoma (2 papers, 2013 to 2022). A malignant, usually aggressive tumor composed of atypical, neoplastic melanocytes. "We observed that cells transfected with siRNAs targeting PKN2 exhibit increased WNT3A-dependent activity of the BAR in A2058 melanoma cells (lane 2)." (PMID 24114839, 2013). "To determine whether PKN1 and PKN2 inhibit Wnt/β-catenin-dependent gene expression in several established melanoma cell lines, we transfected siRNAs targeting PKN1 and PKN2 into A2058, SKMEL5, COLO-829, and Mel-624 cells." (PMID 24114839, 2013). "Because reducing expression of PKN1 and PKN2 elevates Wnt/β-catenin-dependent transcription, we predicted that PKN depletion would promote WNT3A-dependent melanoma cell apoptosis." (PMID 24114839, 2013).
oral squamous cell carcinoma (2 papers, 2020 to 2021). "Particularly, PKN2 was reported as an oncogene in oral squamous cell carcinoma progression." (PMID 34745257, 2021).
asthma (1 paper, 2024). "Genetic markers, specifically protein kinase N2 and protein tyrosine kinase 2, along with breastfeeding duration, were also evaluated for their roles in asthma phenotypes." (PMID 39190449, 2024).
B cell lymphoma (1 paper, 2013). "Pkn2 expression in tumor cells was compared to that seen in normal bone marrow cells, in sorted IgM+ cells from a spleen of a healthy C57BL6 mouse, to the mouse pre-B cell lymphoma cell line (70Z/3), and to the mouse mature B cell lymphoma cell line (CH12)." (PMID 23626802, 2013).
cardiomyopathy (1 paper, 2022). A disease of the heart muscle or myocardium proper. "Here, we demonstrate that the loss of PKN2 in cardiomyocytes has a catastrophic effect on ventricular myocardial development, suggesting that alterations in PKN2 signalling may contribute to congenital cardiac problems/cardiomyopathy." (PMID 35730579, 2022).
congenital heart disease (1 paper, 2022). A heart disease that is present at birth. "The data have clear implications for congenital heart disease both with respect to PKN2 itself and its downstream signalling, particularly in relation to a potential role in the formation of the compact myocardium and left ventricular non-compaction." (PMID 35730579, 2022).
diabetes (1 paper, 2023). "Genes important for metabolic adaptation to diabetes include the transcription factor Clock, playing a role in PT gluconeogenesis and consequent serum glucose concentration in STZ-induced type 1 DM, Kdm1, an epigenetic regulator for salt-sensitive hypertension, and the kinases Pik3c2a, Pkn2." (PMID 37626062, 2023).
dilated cardiomyopathy (1 paper, 2022). Cardiomyopathy which is characterized by dilation and contractile dysfunction of the left and right ventricles. "All PKN isoforms were detected in human hearts, but PKN2 expression increased in dilated cardiomyopathy (DCM) hearts relative to controls, whilst PKN1 and PKN3 declined." (PMID 35730579, 2022). "RNASeq data showed up-regulation of PKN2 in patients with dilated cardiomyopathy, suggesting an involvement in adult heart disease." (PMID 35730579, 2022).
esophageal cancer (1 paper, 2025). A primary or metastatic malignant neoplasm involving the esophagus. "Immunofluorescence staining results showed that PKN2 was expressed on MDSCs in esophageal cancer tissues." (PMID 40069590, 2025). "Therefore, further investigation is necessary to confirm the observed correlation between PKN2 and the clinical characteristics of esophageal cancer patients by expanding the sample size." (PMID 40069590, 2025).
glaucoma (1 paper, 2023). Increased pressure in the eyeball due to obstruction of the outflow of aqueous humor. "Whereas interestingly, genetic variants, such as single nucleotide polymorphisms in exons of PKN2 have been associated with elevated intraocular pressure, which may increase the risk for glaucoma." (PMID 37255536, 2023). "Given the importance of PKN2 in our results, we theorize that AD might play a function in the development of glaucoma disease, however, further studies are needed to support our hypothesis." (PMID 37255536, 2023).
glioblastoma (1 paper, 2025). The most malignant astrocytic tumor (WHO grade IV). "Presumably, the Gol1 aptamer promotes the overexpression of several components of the PI3K-Akt pathway that are positively associated with apoptosis and differentiation and negatively associated with proliferation and cell growth in human glioblastoma cells, such as the CDKN1A and PKN2 genes." (PMID 39940838, 2025).
hepatocellular carcinoma (1 paper, 2022). A malignant tumor that arises from hepatocytes. "Notably, for some cancers, including sarcomas and hepatocellular carcinoma, a high PKN2KO matrisome score was associated with better outcome, suggesting that, in selected contexts, targeting PKN2 in the stroma may be beneficial." (PMID 35081338, 2022).
Hypertension (1 paper, 2022). The presence of chronic increased pressure in the systemic arterial system. "We also demonstrate that PKN2 haploinsufficiency compromises cardiac adaptation to hypertension in adult mouse hearts." (PMID 35730579, 2022). "PKN2 also supports cardiac remodelling in response to hypertension, but has apparently little impact on the aging heart, potentially having a greater effect on the vasculature." (PMID 35730579, 2022). "To gain mechanistic insight into the effects of PKN2 in the cardiac response to hypertension, we used RNASeq to assess the transcriptional differences in the AngII response of hearts from Pkn2Het mice compared with WT littermates." (PMID 35730579, 2022). "To determine if PKN2 may be involved in disease aetiology, we assessed expression in a mouse model of hypertension induced by angiotensin II (AngII; 0.8 mg/kg/d, 7 days)." (PMID 35730579, 2022).
Hypomagnesemia (1 paper, 2022). An abnormally decreased magnesium concentration in the blood. "The confirmed drug-target interactions suggest an attenuation of pulmonary vascular remodeling (inhibition of PDE10A), modulation of Hepatitis C (HCV) viral response (inhibition of PKN2), and hypomagnesemia (inhibition of TRPM6)." (PMID 35551258, 2022).
lymphoma (1 paper, 2013). A malignant (clonal) proliferation of B- lymphocytes or T- lymphocytes which involves the lymph nodes, bone marrow and/or extranodal sites. "Another possibility is that this relative low expression simply reflects the lack of proper references for this measurement, and Pkn2 expression is intrinsically low in these lymphoma cells." (PMID 23626802, 2013).
osteopetrosis (1 paper, 2021). Osteopetrosis, also known as marble bone disease, is a descriptive term that refers to a group of rare, heritable disorders of the skeleton characterized by increased bone density on radiographs. "At seven loci, there was a single putative causal gene: Abca12 at a locus for adult neurogenesis; Epha4 (stress-coping strategy); Pkn2, Slit3, and Pgk1-rs7 (at three different loci for sleep); H60c (home cage activity); and Adcy1 (osteopetrosis)." (PMID 34311762, 2021).
pancreatic cancer (1 paper, 2022). "As the Rho-YAP axis is implicated in CAF function, we next sought to examine whether PKN2 loss could impact the reciprocal interaction between PSCs and pancreatic cancer (PDAC) cells." (PMID 35081338, 2022). "We hypothesized that PKN2 may play a conserved role in the expansion and activation of fibroblasts into cancer-associated fibroblasts (CAFs) during tumor development and focused on pancreatic cancer as the archetype of desmoplastic myofibroblast-rich tumors." (PMID 35081338, 2022).
pancreatic tumor (1 paper, 2022). "Further, deletion of PKN2 in the pancreatic stroma induces more locally invasive, orthotopic pancreatic tumors." (PMID 35081338, 2022). "Deletion of stromal PKN2 induces a switch to an inflammatory CAF phenotype both in vitro and in vivo, and this is associated with more invasive pancreatic tumors." (PMID 35081338, 2022). "Interestingly, in vivo, deletion of stromal PKN2 resulted in more invasive pancreatic tumors, in agreement with studies where myofibroblast phenotype CAFs have been suppressed or ablated." (PMID 35081338, 2022). "We next wished to examine the impact of stromal PKN2 deletion on pancreatic tumors in vivo." (PMID 35081338, 2022). "Targeting stromal PKN2 in a genetic metastatic PDAC model would provide an alternative albeit complex multi-locus model; targeting PKN2 through Cre-Lox recombination would necessitate pancreatic tumor induction through a non-Cre-driven model, such as the KPF mouse." (PMID 35081338, 2022).
peripheral nerve injury (1 paper, 2025). Injury to a peripheral nerve. "PKN2 has been found to regulate the AKT/mTOR pathway and promote the repair of peripheral nerve injury." (PMID 40078537, 2025).
synucleinopathies (1 paper, 2024). "Beyond known PD genes GBA1 and LRRK2, rare variants AD genes (CD33, CR1 and PSEN2) and Aβ toxicity modifiers involved in RhoA/actin cytoskeleton regulation (ARGHEF1, ARHGEF28, MICAL3, PASK, PKN2, PSEN2) were shared risk factors across synucleinopathies." (PMID 38496508, 2024).
tumor (24 papers, 2011 to 2025). "The Pkn2 (protein kinase N2) gene has the ability to inhibit tumor-associated macrophages polarization and tumor growth." (PMID 35565775, 2022). "Pkn2 is a serine/threonine protein kinase, is a target of Rac and Rho GTPases, is a mediator of a variety of cell signals, and has been implicated in tumor cell migration and invasion." (PMID 23626802, 2013). "In addition to the usual inducers, protein kinase N2 (PKN2) protein kinase is equally capable of inducing DUSP6 in tumor-associated macrophages, reducing ERK activity and the anti-inflammatory cytokines IL-4 and IL-10." (PMID 38139370, 2023). "Finally, growth, invasion, and secondary tumor burden are all statistically enhanced in PKN2KO tumors when compared with mice bearing at least one intact PKN2 allele (PKN2WT and PKN2HET)." (PMID 35081338, 2022). "Furthermore, it may also involve modulation of PKN2 function through mutations or alterations in the expression levels of specific genes within various tumor types." (PMID 40515512, 2025). "The GEO datasets revealed a significant elevation in PKN2 expression in ESCC tumor tissues relative to normal tissues." (PMID 40069590, 2025). "It is crucial to investigate therapeutic approaches that can selectively activate PKN2 in tumor cells using nanoparticle‐based delivery systems." (PMID 40515512, 2025). "In a mouse xenograft model, PKN2 has demonstrated the capacity to inhibit tumor growth and suppress M2-type polarization, both in vitro and in vivo." (PMID 40069590, 2025). "In tumors, PKN2 regulates the velocity and trajectory of epithelial bladder cells during cell migration and tumor cell invasion." (PMID 40069590, 2025). "In clinical samples, immunohistochemistry demonstrated that PKN2 expression in tumor tissues was higher than in normal tissues, particularly in stromal cells of tumors." (PMID 40069590, 2025). "PMN-MDSCs decreased the number of CD8+ T cells in tumor tissues, and PKN2 overexpression further increased the number of CD8+ T cells." (PMID 40069590, 2025). "The initial step involved a comparative analysis of PKN2 expression between ESCC tumor tissues and normal tissues." (PMID 40069590, 2025). "The subcutaneous tumor model in BALB/c nude mice was established using HCT116 cells that stably expressed PKN2 or the control vector." (PMID 40515512, 2025). "Given the abundance of immune cells within tumor stromal cells, we sought to ascertain the expression and distribution characteristics of PKN2 in this context." (PMID 40069590, 2025). "It is notable that the role of PKN2 in tumor immunomodulation may be associated with the activation of additional immune cell types and inflammatory vesicles, as well as with cellular and molecular mechanisms that play a pivotal role in the tumor microenvironment." (PMID 40069590, 2025). "PKN2 is highly expressed in EC tumor tissues compared to normal tissues, especially in tumor-infiltrated PMN-MDSCs." (PMID 40069590, 2025). "Our findings indicated a significant correlation between PKN2 expression in PMN-MDSCs of tumor tissues and tumor stage." (PMID 40069590, 2025). "In TAM, in colon cancer cells, PKN2-inducible DUSP6 leads to the suppression of tumor-associated M2 macrophage polarization and tumor growth, through the inhibition of the ERK1/2, IL-4, and IL-10 cascade." (PMID 38139370, 2023). "This gives confidence that the alterations to the tumor matrisome result from deletion of PKN2 in PSCs and CAFs." (PMID 35081338, 2022). "In vivo, stromal deletion of PKN2 also resulted in a shift from myCAF to iCAF signatures in orthotopic murine tumours, accompanied by enhanced EMT and IL6‐JAK‐STAT3 signalling." (PMID 35533046, 2022). "This implies that the role for PKN2 in myofibroblast function delineated in PSCs is conserved in CAF populations in orthotopic tumours." (PMID 35533046, 2022).
tumor (continued). "Development of PKN2 selective inhibitors, which do not exhibit the confounding off-target effects of currently available compounds, such as Y27632, Fasudil, and PKC412, would provide a pharmacological route for addressing specific PKN2 roles in tumor biology." (PMID 35081338, 2022). "Understanding how PKN2 contributes to specific CAF traits thus has the potential to define novel ways to modulate PDAC tumor biology." (PMID 35081338, 2022). "Previous studies indicated that overexpression of PKN2 is involved in cell proliferation by regulating ERK/MAPK or AKT signaling pathways and inhibit M2 phenotype polarization of tumor-associated macrophages in CRC cells." (PMID 34663329, 2021). "We also found a decreased mRNA expression of PKN2 in PTC tumor cells, as compared with human normal thyroid cells." (PMID 34745257, 2021). "The results showed that tumours with lower expression of circ_SEPT9 had higher level of miR‐1225, lower PKN2 mRNA and protein level." (PMID 33090705, 2020). "Our research has discovered a novel mechanism for PKN2 regulation which would provide a new thought about targeted therapy for tumour progression." (PMID 33090705, 2020). "What's more, tumour tissue had more abundant expression of PKN2 than the compared adjacent normal tissue." (PMID 33090705, 2020). "Overexpression of PKN2 enhanced the tumour growth, migration and invasion ability, while the ability significantly decreased in the presence of PKN2 siRNAs in UM1 cells." (PMID 33090705, 2020). "First, the Serine/threonine-protein kinase N2 (PKN2), which plays a role in the regulation of cell cycle progression, actin cytoskeleton assembly, cell migration, cell adhesion, tumor cell invasion and transcription activation signaling processes." (PMID 31675377, 2019). "PKN2 regulates epithelial bladder cells speed and directmovement during cell migration and tumor cell invasion." (PMID 29368606, 2018). "The number of CD68+ cells was similar in both high (++& +++) and low (−&+) PKN2 expression tumor tissues." (PMID 29368606, 2018). "The mRNA level of IL4 and IL10 was significantly decreased in PKN2-WT tumor cells, but increased in PKN2-K686R tumor cells, indicating that IL4 and IL10 are negatively regulated by PKN2." (PMID 29368606, 2018). "PKN2 inhibited tumor growth in mice xenograft model and inhibited M2 phenotype polarization both in vitro and in vivo." (PMID 29368606, 2018). "The effects of PKN2 on tumor growth and TAM polarization were investigated both in vitro and in vivo." (PMID 29368606, 2018). "PKN2-K686R led to significantly increased CD206+cells and decreased CD16/32+ cells in tumor tissues while ectopic expression of PKN2-WT led to decreased CD206+ cells and increased CD16/32+ cells." (PMID 29368606, 2018). "To explore the effects of PKN2 on tumor proliferation and macrophage polarization, we generated HCT116 cells stably expressing wild-type PKN2 (PKN2-WT), dominant negative PKN2 (PKN2-K686R) and null vector (Vector) lentivirus." (PMID 29368606, 2018). "In the tumour cell line 5637 with relatively enriched expression of PKN2 compared to other cells tested, we were able to detect a strong phenotype just by depleting PKN2, with PKN1 depletion having a weaker effect and PKN3 none at all." (PMID 21754995, 2011). "In light of these findings, PKN2 may represent a promising therapeutic target in tumor immunotherapy." (PMID 40069590, 2025). "However, a notable increase in PKN2 expression was observed in tumor-derived PMN-MDSCs compared to their spleen-derived counterparts." (PMID 40069590, 2025). "PKN2 appears to have a dual role in promoting or suppressing cancer, depending on the tumor type." (PMID 40515512, 2025). "Further investigation into the tissue‐specific functions of PKN2 may elucidate the dual role of PKN2 in cancer development across different tumor types." (PMID 40515512, 2025).